SLC25A28 (solute carrier family 25 member 28)
Description:
Mitochondrial iron transporter that mediates iron uptake. Probably required for heme synthesis of hemoproteins and Fe-S cluster assembly in non-erythroid cells.
Synonyms: MRS3/4; MFRN2; NPD016; MRS4L
Tractability: Antibody: UniProt predicts a signal peptide or a membrane-spanning region.
Gene: Protein-coding gene on chromosome 10 (99,610,518 to 99,622,793, reverse strand). Ensembl gene ENSG00000155287.
Subcellular location: Mitochondrion inner membrane (Isoform 1); Mitochondrion inner membrane (Isoform 2)
Pathways (Reactome):
Metabolism: Mitochondrial iron-sulfur cluster biogenesis
Gene Ontology:
Molecular function: ferrous iron transmembrane transporter activity; iron ion transmembrane transporter activity
Biological process: iron ion transmembrane transport
Cellular component: mitochondrion; mitochondrial inner membrane
Genetic constraint (gnomAD): Loss-of-function variants: 10 observed, 29.46 expected, observed/expected ratio (o/e) 0.34, 90% interval 0.21 to 0.58. The upper end of that interval is the gene's LOEUF score, 0.58, which puts it in group 2 of 6, group 1 being the genes least tolerant of losing a copy. Missense variants: 231 observed, 438.16 expected, observed/expected ratio (o/e) 0.53, 90% interval 0.47 to 0.59. Synonymous variants: 198 observed, 182.6 expected, observed/expected ratio (o/e) 1.08, 90% interval 0.96 to 1.22.
Homologues: Orthologues: chimpanzee SLC25A28 (100% identical), macaque SLC25A28 (100% identical), dog SLC25A28 (99% identical), pig SLC25A28 (99% identical), guinea pig SLC25A28 (98% identical), rabbit SLC25A28 (98% identical), mouse Slc25a28 (98% identical), rat Slc25a28 (97% identical), tropical clawed frog slc25a28 (76% identical), zebrafish slc25a28 (70% identical). Paralogues in human: SLC25A37 (61% identical), SLC25A13 (26% identical), SLC25A12 (26% identical), SLC25A23 (22% identical), SLC25A39 (22% identical), SLC25A19 (21% identical), SLC25A33 (21% identical), SLC25A25 (21% identical), SLC25A18 (21% identical), SLC25A21 (21% identical), SLC25A24 (21% identical), SLC25A40 (21% identical), and 37 more.
Diseases named in the same sentence as SLC25A28 in open-access papers:
SLC25A28 is named in the same sentence as 39 diseases in open-access papers, as found by Europe PMC text mining. Sharing a sentence is not in itself a finding about the gene and the disease. The quoted sentences say what the papers report.
glioma (4 papers, 2014 to 2023). A benign or malignant brain and spinal cord tumor that arises from glial cells (astrocytes, oligodendrocytes, ependymal cells). "The SLC25A28 gene encodes a mitochondrial iron uptake transporter (Mfrn2), which participates in As2O3-induced cell killing in glioma." (PMID 33489900, 2020).
osteosarcoma (4 papers, 2020 to 2024). A usually aggressive malignant bone-forming mesenchymal neoplasm, predominantly affecting adolescents and young adults. "Previous research has also affirmed that knockdown of SLC25A28 decreased the production of reactive oxygen species in osteosarcoma." (PMID 38736904, 2024). "Mitochondrial iron transporters mitoferrin 1 (SLC25A37) and mitoferrin 2 (SLC25A28)-mediated iron accumulation increase ROS mediated-carcinogenesis in osteosarcoma." (PMID 36185202, 2022). "Interestingly, our work revealed that mitochondrion-mediated iron accumulation increased ROS production in both osteosarcoma cell lines, whereas knock-down of mitoferrin 1 (SLC25A37) and mitoferrin 2 (SLC25A28) decreased this phenomenon." (PMID 32831652, 2020).
pancreatic cancer (3 papers, 2020 to 2022). "After identifying FBXL5, SLC25A28, and SLC25A37 as substrate RNAs of ALKBH5, we further investigated the relevant mechanism associated with pancreatic cancer progression." (PMID 34733841, 2021). "Mechanistically, the RNA stabilities of FBXL5 and SLC25A28, and the AS of SLC25A37 were affected, which led to their upregulation in pancreatic cancer cell line." (PMID 34733841, 2021). "Interestingly, the expression of SLC25A37 in patients with pancreatic cancer correlated negatively with patient survival, yet the expression of SLC25A28 did not correlate with survival." (PMID 36359860, 2022).
breast carcinoma (2 papers, 2023 to 2024). "Thus, TFR2 and SLC25A28 (mitoferrin-2) levels are markedly decreased in breast cancer cells with MEMO1 knockdown and knockout." (PMID 38640016, 2024). "Conversely, knockdown or knockout of MEMO1 in breast cancer cells resulted in a statistically significant decrease in the expression levels of TFR1, TFR2, ACO1, and SLC25A28." (PMID 38640016, 2024). "SLC25A28 (mitoferrin-2), which mediates iron uptake in mitochondria, displayed GOF-GI with MEMO1, its knockdown selectively suppressing proliferation of MEMO1-overexpressing breast cancer cells." (PMID 38640016, 2024). "ACO1, SLC25A28, and PLOD1 showed GOF interactions with MEMO1 in breast cancer cells." (PMID 38640016, 2024). "Remarkably, ACO1 knockdown only inhibited proliferation of the high-MEMO1 cells, but not MEMO1 knockout breast cancer cells, while SLC25A28 and PLOD1 knockdowns showed some effect in all cell lines, but a stronger inhibition in the high-MEMO1 cells than in MEMO1 knockout." (PMID 38640016, 2024).
colorectal cancer (2 papers, 2022 to 2024). A primary or metastatic malignant neoplasm that affects the colon or rectum. "NKX2-3 and SLC25A28 were associated with CD, IBD, colorectal cancer, type I diabetes mellitus, and rheumatoid arthritis." (PMID 35464478, 2022). "In addition to the expected association with anaemia-related phenotypes, the only other Bonferroni-significant associations of individual biological pathways that persisted in colocalization were EPAS1 with hypertension and SLC25A28 with colorectal cancer and benign neoplasm of colon." (PMID 39643614, 2024).
melanoma (2 papers, 2019 to 2024). A malignant, usually aggressive tumor composed of atypical, neoplastic melanocytes. "By comparison, MEMO1 knockdown or knockout in melanoma cells decreased only the expression level of TFR2, the effect on SLC25A28 knockdown being difficult to interpret." (PMID 38640016, 2024).
cataract (1 paper, 2025). Partial or complete opacity of the crystalline lens of one or both eyes that decreases visual acuity and eventually results in blindness. "We generate knockout mice for Slc25a28 revealing that, except for cataracts in some mice, these animals are normal; suggesting inhibition of SLC25A28 is unlikely to be associated with profound toxicity." (PMID 40968372, 2025). "We were drawn to focus on a knockout of Slc25a28, noting that this mutant line had been scored as having cataracts in some mice, but no other phenotypic traits." (PMID 40968372, 2025). "Reassuringly, as part of this study we identified several gene pairs such as SLC25A37/SLC25A28 and CNOT7/CNOT8 that represent attractive targets for further drug development, with Slc25a28 knockout mice being viable and fertile with no overt phenotypes, other than cataracts in some mice." (PMID 40968372, 2025).
Congenital sideroblastic anemia (1 paper, 2021). "Congenital sideroblastic anemia (CSA) is most frequently caused by X-linked mutations in ALAS2 (Delta-aminolevulinate synthase 2, XLSA), followed by ABCB7 (ATP Binding Cassette Subfamily B Member 7), SLC25A28 (Solute Carrier Family 25 Member 28) and GLRX5 (Glutaredoxin 5)." (PMID 33672223, 2021).
COVID-19 (1 paper, 2021). A disease caused by infection with severe acute respiratory syndrome coronavirus 2. "Eight ISGs were downregulated in Asymptomatic as compared with severe COVID-19 cases; CNP, CSF1, IRF1, IFITM10, IRF2BP2, IRF2BPL, SLC25A28 and SOCS3." (PMID 34824360, 2021).
Glucose intolerance (1 paper, 2024). Glucose intolerance (GI) can be defined as dysglycemia that comprises both prediabetes and diabetes. "In our study, we used adenovirus injection to overexpression SLC25A28 whole body wide and affirmed a promoting obesity function of SLC25A28 in diet-induced obesity as well as glucose intolerance impairment." (PMID 38736904, 2024).
intracerebral hemorrhage (1 paper, 2025). A cerebrovascular disorder characterized by bleeding into one or both cerebral hemispheres including the basal ganglia and the cerebral cortex. "Our prior research demonstrated that the knockout of the mitochondrial iron transporter SLC25A28 alleviates microglial activation and improves outcomes in a mouse model of intracerebral hemorrhage." (PMID 41177991, 2025).
iron overload (1 paper, 2024). "Intracellular iron is transported to mitochondria via SLC25A37 and SLC25A28, and thus impaired intracellular and mitochondrial iron homeostasis has been identified as a hallmark of iron overload, which in turn accelerates the process of iron overload." (PMID 39767635, 2024).
Obesity (1 paper, 2024). Accumulation of substantial excess body fat. "In summary, this study demonstrated that overexpression of SLC25A28 promotes lipid accumulation and adipogenesis in mice, impaired glucose tolerance, and exacerbated diet-induced obesity." (PMID 38736904, 2024). "Our findings affirm that SLC25A28 overexpression contributes to increased weight gain and accelerates the occurrence of obesity, as mice with SLC25A28 overexpression manifested an increase in adipocyte size and serum adiponectin, while serum FGF21 decreased." (PMID 38736904, 2024). "Data from the current study indicate that SLC25A28 overexpression promotes diet-induced obesity and accelerates lipid accumulation by regulating hormone secretion and inhibiting lipolysis in adipose tissue." (PMID 38736904, 2024).
schizophrenia (1 paper, 2023). A major psychotic disorder characterized by abnormalities in the perception or expression of reality. "There is no previous evidence of association between SLC25A28 and schizophrenia or related disorders." (PMID 37881554, 2023).
spinal cord injury (1 paper, 2025). Penetrating and non-penetrating injuries to the spinal cord resulting from traumatic external forces (e.g., WOUNDS, GUNSHOT; WHIPLASH INJURIES; etc.). "In this study, we investigate the role of SLC25A28 in neuroinflammation following spinal cord injury (SCI)." (PMID 41177991, 2025).
cancer (11 papers, 2014 to 2025). A tumor composed of atypical neoplastic, often pleomorphic cells that invade other tissues. "We show that SLC25A28 is an attractive target since its synthetic lethal paralog partner SLC25A37 is homozygously deleted pan-cancer." (PMID 40968372, 2025). "For several genes, most notably CNOT7, GDI1 and SLC25A37, there are a subset of tumours that showed homozygous deletion and thus inhibition/suppression of CNOT8, GDI2 or SLC25A28, respectively, would be predicted to provoke cellular lethality/reduced cancer cell fitness." (PMID 40968372, 2025). "The role of SLC25A28 in cancer development remains unexplored." (PMID 38833016, 2024).
tumor (8 papers, 2021 to 2025). "The tumor-suppressor roles of SLC25A37 and SLC25A28 have been confirmed since they were involved in tumor cell growth, ROS production, mitochondrial iron uptake, and ferroptosis." (PMID 35936737, 2022). "In order to ensure whether butyrate suppresses BC tumor growth by targeting TLR4-PDXK/SLC25A28 signalling pathway, T47D cells were transfected with the plasmid expressing TLR4 or empty plasmid, and simultaneously treated with 5.0 mM butyrate." (PMID 38833016, 2024). "Moreover, decreased PDXK protein expression and decreased SLC25A28 protein expression were found in clinical BC tumor specimens." (PMID 38833016, 2024). "Similarly, the relative weaker correlation of RNA expression between SLC25A28 and ALKBH5 in tumor samples may also arise from other uncharacterized mechanisms in regulating SLC25A28." (PMID 34733841, 2021). "In summary, butyrate significantly inhibits the growth of BC tumor and facilitates the expression of PDXK and SLC25A28 in a dose-dependent manner." (PMID 38833016, 2024). "However, despite of positive regulation of ALKBH5 on SLC25A28 and SLC25A37 observed here, we found that these two proteins were overexpressed in the tumor cells of PDAC." (PMID 34733841, 2021). "Previous study found impaired PINK1 and PRKN expression could promote the degradation of SLC25A37 and SLC25A28 and increase the mitochondrial iron accumulation, which lead to AIM2-mediated HMGB1 release that further induced expression of CD274/PD-L1 in tumor cells." (PMID 36612054, 2022).
neurological diseases (2 papers, 2021 to 2025). "Determining whether the SLC25A28–heme–NOX2 axis represents a convergent mechanism across neurological diseases will require further study." (PMID 41177991, 2025).
SLC25A28 also shares sentences with these, for which no sentence is quoted: atherosclerosis (2 papers); anaemia (1); benign neoplasm of colon (1); endothelial dysfunction (1); Friedreich ataxia (1); head and neck cancer (1); hepatocellular carcinoma (1); Hypertension (1); iron deficiency (1); leukemia (1); liver cancer (1); liver fibrosis (1); lung carcinoma (1); metabolic syndrome (1); myopathy (1); ovarian carcinoma (1); pancreatic ductal adenocarcinoma (1); Parkinson’s disease 7 (1); pulmonary fibrosis (1); rheumatoid arthritis (1); type 1 diabetes mellitus (1).